E2F8 (E2F transcription factor 8)
Diseases named in the same sentence as E2F8 in open-access papers (continued):
Sharing a sentence is not in itself a finding about the gene and the disease.
cervical cancer (8 papers, 2020 to 2024). A primary or metastatic malignant neoplasm involving the cervix. "To determine whether E2F8 expression in tissues was associated with the clinicopathologic characteristics of cervical cancer, we evaluated the expression of E2F8 in cervical cancer tissue (n =80) and corresponding normal tissue (n =20)." (PMID 31929759, 2020). "Our study suggests that E2F8 is a promising prognostic factor and target for cervical cancer treatments." (PMID 31929759, 2020). "In conclusion, our study suggests that E2F8 is highly correlated with the progression-free survival of cervical cancer patients." (PMID 31929759, 2020). "Accordingly, in this study, the molecular function and clinical significance of E2F8 expression was investigated in cervical cancer cell lines." (PMID 31929759, 2020). "Our results show that E2F8 strengthened the growth, migration, and invasion of cervical cancer cells through an EMT signaling pathway." (PMID 31929759, 2020). "Kaplan-Meier survival analysis demonstrated that cervical cancer patients with low E2F8 levels exhibited longer overall survival and disease-free survival than cervical cancer patients with high E2F8 levels (p=0.035 and 0.028)." (PMID 31929759, 2020). "Our results suggest that E2F8 can contribute to the growth, invasion, and recurrence of cervical cancer through induction of the EMT." (PMID 31929759, 2020). "E2F8 knockdown in cervical cancer cell lines (HeLa and ME180) showed significant decrease in wound-healing." (PMID 31929759, 2020). "In summary, our research suggests that E2F8 is correlated with the progression of cervical cancer via EMT signaling pathways." (PMID 31929759, 2020). "Our findings showed that downregulated E2F8 expression was correlated with decreased cell growth, migration, and invasion of cervical cancer cells." (PMID 31929759, 2020). "To demonstrate the function of E2F8 in cell proliferation, migration and invasion, we knocked down E2F8 in cervical cancer cell lines; in vitro and in vivo experiments using this knockdown showed that E2F8 potently induced the expression of epithelial-mesenchymal transition (EMT) markers." (PMID 31929759, 2020). "Our findings suggested that E2F8 could potentially represent a novel biomarker and therapeutic target for cervical cancer." (PMID 31929759, 2020). "In this study, we investigated the functional role of E2F8 in the progression of cervical cancer." (PMID 31929759, 2020). "The present study explored the molecular function of E2F8 expression in cervical cancer cell lines." (PMID 31929759, 2020). "Next, we examined the effects of E2F8 in cervical cancer cells." (PMID 31929759, 2020). "Therefore, the same cell lines were used to assess migration in si- and sh-E2F8 transfected cervical cancer cells." (PMID 31929759, 2020). "However, the clinical significance and biological function of E2F8 in gynecological cancer, especially cervical cancer, remains unknown." (PMID 31929759, 2020). "Moreover, E2F8 knockdown altered the cell growth, migration, and invasion of cervical cancer cells." (PMID 31929759, 2020). "We investigated whether E2F8 affects the invasion and migration of cervical cancer cells." (PMID 31929759, 2020). "The E2F8 expression in cervical cancer tissues was more than 11.07 times that of non-cancerous tissues (p= 0.001)." (PMID 31929759, 2020). "We found that E2F8 expression was higher in cervical cancer tissues than that in non-cancerous tissues." (PMID 31929759, 2020). "Finally, clinical data confirmed that E2F8 was a significant predictive factor for progression-free survival, and that patients with cervical cancer who exhibited high expression of E2F8 showed high FIGO stages and frequent recurrence rates compared to patients with low E2F8 expression." (PMID 31929759, 2020). "However, the biological role and clinical significance of E2F8 in the progression of cervical cancer has not yet been identified in relation to the epithelial-mesenchymal transition (EMT)." (PMID 31929759, 2020).
cervical cancer (continued). "However, it is not yet known whether E2F8 is involved in the progression of cervical cancer." (PMID 31929759, 2020).
glioblastoma (7 papers, 2020 to 2025). The most malignant astrocytic tumor (WHO grade IV). "Specifically, we found that three E2F members showed decreased expression upon radiation: E2F1, E2F2, and E2F8, all of which have been previously implicated in glioblastoma development." (PMID 32488114, 2020). "E2F2 has been implicated in regulation of cancer stem cell (CSC) properties by various microRNAs and necessary for self-renewal of stem cells and radioresistance of glioblastoma, whereas E2F8 is thought to be associated with tumorigenesis and radioresistance as well as with EMT." (PMID 40316727, 2025). "In conclusion, a deep examination of E2F members provides new insights into the mechanisms of glioblastoma outcomes and recurrence after bevacizumab (BVZ) treatment, specifically those associated with E2F8." (PMID 39061176, 2024). "Based on what is known regarding the regulation of E2F transcription factors, we decided to test if the previously identified Msi1 direct targets CDK6, CDKN1A/p21, CDKN1B/p27 affect E2F2 and E2F8 levels in glioblastoma cells." (PMID 33804958, 2021). "Although still poorly characterized in the context of glioblastoma, E2F8 drives an oncogenic phenotype in glioblastoma." (PMID 32488114, 2020). "In the Sun Brain Statistics, E2F8 was also overexpressed in anaplastic astrocytoma (fold change = 4.196), glioblastoma (fold change = 7.097), and oligodendroglioma (fold change = 3.341) compared to normal samples." (PMID 33381564, 2020). "Finally, single-cell analysis of glioblastoma tumors identified a cell cluster showing increased expression of cell cycle-related genes including E2F8 and several genes downregulated in U251/U343Msi1 KO cells." (PMID 33804958, 2021). "In a recent study to evaluate early changes in expression in glioblastoma cells after radiation, we determined that down-regulation of genes implicated in the cell cycle, DNA repair and DNA replication is likely the result of decreased expression of FOXM1, E2F1, E2F2 and E2F8." (PMID 33804958, 2021).
liver cancer (7 papers, 2018 to 2025). An epithelial or non-epithelial malignant neoplasm that arises from the liver. "E2F8 enhances cisplatin resistance in liver cancer cells by activating NUSAP1, which in turn inhibits DNA damage." (PMID 40535133, 2025). "E2F8 is highly expressed in various tumors and promotes tumor progression, and serves as a therapeutic target in lung and liver cancers." (PMID 30967995, 2019). "E2F8 transcriptionally activates the target gene NUSAP1, thereby alleviating DNA damage and mediating cisplatin resistance in liver cancer cells." (PMID 40535133, 2025).
melanoma (7 papers, 2011 to 2025). A malignant, usually aggressive tumor composed of atypical, neoplastic melanocytes. "Importantly, upon adoptive transfer, the Dbp-deficient and E2f8-deficient Th9 cells enhances and suppresses tumor growth, respectively, in mouse models of melanoma and fibrosarcoma in vivo." (PMID 36241625, 2022). "The expression levels of E2F2, E2F7, and E2F8 in the C4 melanoma cell subgroup were significantly higher compared to other subgroups." (PMID 39781353, 2025). "Other contributing factors are that E2f8 is involved in transcription, and its gene copy number is increased in melanoma." (PMID 36559040, 2022). "The opposing functions of DBP and E2F8 as enhancer and repressor respectively, in Th9 cells contribute to Th9-medaited anti-tumor effects in experimental models of melanoma and fibrosarcoma and suggest their biological significance in cancer immunotherapy." (PMID 36241625, 2022). "However, there are few reports of E2f8 activity in melanoma." (PMID 36559040, 2022). "We validated the heterogeneity and aberration status within single biopsies by fluorescent in situ hybridization of four affected and transcriptionally up-regulated genes E2F8, ETV4, EZH2 and FAM84B in 11 melanoma cell lines." (PMID 21569352, 2011).
prostate carcinoma (6 papers, 2016 to 2024). A carcinoma that arises from epithelial cells of the prostate gland. "In prostate cancer, an increased E2F8 level is associated with prostate cancer metastasis, and the patients with a high level of E2F8 had significantly worse overall survival." (PMID 38605607, 2024). "As a small molecule inhibitor of E2F8, MA may serve as a potential lead compound to overcome therapy resistance in prostate cancer caused by AR remodeling." (PMID 38605607, 2024). "Our results provide a basis for future investigations aiming at elucidating the molecular mechanisms underlying the expression or activity of E2F8 in prostate cancer, which assists to understand the role of E2F8 in CRPC biology and to develop novel cell cycle‐targeted therapeutic strategies." (PMID 27683099, 2016). "In addition, we found that E2F8 is associated with poor survival of prostate cancer patients." (PMID 27683099, 2016). "For the first time, we investigated the anti‐cancer properties of MA targeting prostate cancer in vitro and in vivo and demonstrated that MA abrogated the AR‐FL and its splice variance AR‐V7 transcription via inhibition of E2F8 function." (PMID 38605607, 2024). "A recent study suggested that an immunosuppressive drug cyclosporin A inhibits E2F8 transcription factor via MELK in prostate cancer." (PMID 38605607, 2024). "Identification of E2F8 as a novel regulator of AR biogenesis and transcription provides a new therapeutic target in castration‐resistant prostate cancer." (PMID 38605607, 2024). "In this study, we demonstrated that MA, a small molecule inhibitor from a marine sponge, represses AR transcription via the atypical E2F transcriptional factor E2F8 and inhibits prostate cancer cell proliferation in vitro and in vivo." (PMID 38605607, 2024). "We identified E2F8 as a reliable molecular target of MA and a novel regulator of AR transcription in prostate cancer." (PMID 38605607, 2024). "In short, few studies have focused on the function of these three E2Fs in PCa, and the roles of E2F4, E2F7, and E2F8 in prostate cancer remain to be explored." (PMID 35531101, 2022). "In regard to E2F8, it has been reported that geraniol can suppress prostate cancer growth by down-regulating E2F8." (PMID 35531101, 2022). "Our study reveals that E2F8 exerts pro‐oncogenic activity in prostate cancer via G2/M cell cycle regulation." (PMID 27683099, 2016). "To assess the effect of E2F8 on clinical outcome, we compared overall survival in the prostate cancer patients with low‐ and high‐expression of E2F8." (PMID 27683099, 2016). "Our results indicate that E2F8 is required for the growth of prostate cancer cells and is aberrantly expressed in metastatic prostate cancer." (PMID 27683099, 2016). "Master regulator analysis using the prostate cancer‐specific regulatory interactome identified that the transcription factor E2F8 as a specific target molecule regulates geraniol‐specific cell cycle signatures." (PMID 27683099, 2016). "Thus, blocking the interaction between E2F8 and DNA successfully abrogates AR synthesis and AR‐regulated genes and provides a novel mechanism for controlling treatment‐resistant prostate cancer." (PMID 38605607, 2024). "Through detailed molecular studies of the marine alkaloid manzamine A (MA), we identified transcription factor E2F8 as a previously unknown regulator of AR transcription that prevents AR synthesis in prostate cancer cells." (PMID 38605607, 2024). "This novel mechanism of blocking AR biogenesis via E2F8 may provide an opportunity to control therapy‐resistant prostate cancer over the currently used AR antagonists designed to target different parts of the AR gene." (PMID 38605607, 2024). "Downregulation of E2F8 has been reported as a driver for prostate cancer growth suppression, and if cancer selectivity could be obtained, might represent a good target for stabilizing growth inhibition in GBM." (PMID 34359681, 2021).
prostate carcinoma (continued). "In addition, we demonstrate that the overexpression of E2F8 has clinically relevant prognostic significance in prostate cancer." (PMID 27683099, 2016). "Therefore, our study provides insight into the role of E2F8 in prostate cancer biology and therapeutics." (PMID 27683099, 2016). "In addition, our findings suggest that E2F8 plays a crucial role in the regulation of G2/M cell cycle in prostate cancer cells." (PMID 27683099, 2016). "However, we focused on understanding the role of E2F8 in regulating AR due to the lack of E2F8 studies in prostate cancer." (PMID 38605607, 2024).
colon cancer (5 papers, 2020 to 2023). "Additionally, E2F3, E2F4, E2F7 and E2F8 were significantly associated with the stages of colon cancer." (PMID 32117628, 2020). "Our studies indicated that the deregulation of E2F1, E2F2, E2F3, E2F5, E2F7 and E2F8 in colon cancer tissues might play a vital role in colon cancer oncogenesis, which could be promising diagnostic biomarkers for LUAD." (PMID 32117628, 2020). "In addition, the expression of E2F3, E2F4, E2F7 and E2F8 were significantly associated with tumor stages and overall survival of the patients with colon cancer, suggesting that they may serve as potential therapeutic targets for colon cancer." (PMID 32117628, 2020). "Knockdown of E2F8 suppresses cell proliferation in colon cancer cells by modulating the NF-KB pathway." (PMID 33224876, 2020). "The results demonstrated that the expression levels of E2F3, E2F4, E2F7 and E2F8 displayed significant correlation with the tumor stage in patients with colon cancer while other members in E2F family in normal group and tumor group did not significantly differ." (PMID 32117628, 2020). "Hence, more experiments should be performed to explore the potential roles of E2F8 in colon cancer." (PMID 32117628, 2020). "As for E2F8, although there were no studies reporting its roles in colon cancer, our findings unveiled its different expressions between normal tissues and colon cancer tissues, apart from its association with tumor stage." (PMID 32117628, 2020). "Our study implied that E2F3, E2F4, E2F7 and E2F8 are potential targets of precision therapy for patients with colon cancer while E2F1, E2F2, E3F3, E2F5, E2F7 and E2F8 are potential biomarkers for the diagnosis of colon cancer." (PMID 32117628, 2020). "Previous studies have identified E2F8 as a biomarker for colon cancer, but they did not evaluate the potential role of SNHG1-RFWD3-E2F8 ceRNA network interaction in rectum cancer." (PMID 34178670, 2021).
gastric cancer (5 papers, 2015 to 2024). A primary or metastatic malignant neoplasm involving the stomach. "The results showed that the higher transcriptional levels of both E2F2 and E2F8 were associated with better overall survival in gastric cancer patients." (PMID 35371973, 2022). "The E2F proteins are encoded by eight genes (i.e. E2F1 to E2F8), each of which may play a specific role in gastric cancer." (PMID 34136392, 2021). "Cellular experiments confirmed that the transcriptional level of E2F2 and E2F8 affected cell proliferation and migration in gastric cancer cell lines." (PMID 38371373, 2024). "The qPCR assay results showed the mRNA levels of E2F2 and E2F8 were significantly upregulated in the gastric cancer tissues compared with the corresponding normal tissues, which was consistent with both the transcriptomic database and the findings of previous studies." (PMID 38371373, 2024). "To date, the members of E2F proteins include E2F1- E2F8 and among of them, E2F1, 2, 3, 4, 5, and 7 proteins were all significantly overexpressed in gastric cancer in the current study." (PMID 25646628, 2015).
papillary thyroid cancer (5 papers, 2017 to 2021). "However, the clinical significance and biological function of E2F8 in papillary thyroid cancer remain unknown." (PMID 28270228, 2017).
cholangiocarcinoma (3 papers, 2020 to 2023). A carcinoma that arises from the intrahepatic biliary tree (intrahepatic cholangiocarcinoma) or from the junction, or adjacent to the junction, of the right and left hepatic ducts (hilar cholangiocarcinoma). "The lncRNA SNHG6 improves E2F8 expression by associating with miR-101-3p, thus promoting proliferation and angiogenesis in cholangiocarcinoma." (PMID 40636922, 2023).
colorectal cancer (3 papers, 2020 to 2021). A primary or metastatic malignant neoplasm that affects the colon or rectum. "To explore the up-steam of SNRPN, we found by luciferase reporter assay and chromosomal immunoprecipitation assay that E2F8 was a transcriptional regulator up-steam of SNRPN in colorectal cancer." (PMID 33224876, 2020). "The present study provides important evidence of the axis of E2F8/SNRPN in colorectal cancer." (PMID 33224876, 2020).
esophageal squamous cell carcinoma (3 papers, 2020 to 2023). Esophageal squamous cell carcinoma (ESCC) is a type of esophageal carcinoma (EC) that can affect any part of the esophagus, but is usually located in the upper or middle third. "While previous work in fibroblasts suggested that forced expression of E2F8 reduced cell proliferation through a negative feedback loop, additional research in esophageal squamous cell carcinoma identified E2F8 as a promoter of proliferation through CCND1/p21 signaling." (PMID 38086808, 2023).
neuroblastoma (3 papers, 2021 to 2023). Neuroblastoma (NB) is the most common solid, extracranial childhood tumor. "E2F8 was associated with the overall survival of neuroblastoma in TARGET, GSE16476 and GSE85047 datasets." (PMID 35764946, 2022). "E2F transcription factors E2F1, E2F3, E2F7 and E2F8 were all associated with the event free survival of neuroblastoma in TARGET, GSE16476 and GSE85047 datasets." (PMID 35764946, 2022). "Last, our study defined for the first time through a cross-species integrative transcriptomics approach putative master regulators for MYCN-driven neuroblastoma tumor development and revealed FOXM1 and the DREAM complex members MYBL2 and E2F8 as top-scoring candidates." (PMID 34638267, 2021).
non-small cell lung carcinoma (3 papers, 2017 to 2021). A group of at least three distinct histological types of lung cancer, including non-small cell squamous cell carcinoma, adenocarcinoma, and large cell carcinoma. "Additionally, poorer OS in non-small cell lung cancer patients with E2F8 overexpression has been observed than in those without." (PMID 31990034, 2020).
pancreatic cancer (3 papers, 2020 to 2024). "Silencing of E2F1 and E2F8 in PANC‐1 pancreatic tumor cells inhibited cell proliferation and impaired cell spreading and migration." (PMID 38686617, 2024). "E2F1 and E2F8 mainly positively correlate with the same genes in PDAC tissues, suggesting similar and redundant functions, as observed experimentally in pancreatic cancer cells." (PMID 38686617, 2024).
Breast Invasive Carcinoma (2 papers, 2016 to 2023). "Furthermore, the Kaplan–Meier dataset plotter was performed to reveal that high expression of MYBL2, HOXC13, and E2F8 had a poor RFS rate in invasive breast cancers." (PMID 36814821, 2023). "Moreover, the Kaplan–Meier plotter data revealed that the patients with both high E2F8 mRNA levels and decreased T cells (CD4+ T cells, CD8+ T cells, and macrophage cells) had a worse RFS compared with the patients with enriched CD4+ T cells in breast invasive carcinoma." (PMID 36814821, 2023).
cervical squamous cell carcinoma (2 papers, 2020 to 2023). A squamous cell carcinoma arising from the cervical epithelium. "We also found increased expression for E2F8 in cervical squamous cell carcinoma tissues compared with that found in normal cervical tissues with mRNA fold changes of 2.557 (p = 9.81E−5) and 2.751 (p = 1.96E−5) in the Zhai Cervix and Scotto Cervix datasets, respectively." (PMID 33061852, 2020).